MX1 (MX dynamin like GTPase 1)
Diseases named in the same sentence as MX1 in open-access papers (continued):
Sharing a sentence is not in itself a finding about the gene and the disease.
infection (continued). "Furthermore, all identified infection-associated ISG genes (MX1, MX2, OAS1Y/Z, OAS2, ISG15, IFI6, IFI44 and RSAD2) showed lower expression values in Holstein infected cells relative to Sahiwal." (PMID 35061738, 2022). "While i.v. injection of 3pRNA prior to IAV infection was protective in both mouse strains (as assessed by IAV-induced weight loss and virus replication in the airways at day 5 post-infection), it was particularly potent and long-lasting in mice expressing a functional Mx1 protein." (PMID 35891527, 2022). "However, three different studies associated the lower levels of MX1 expression in the chronic phase of infection with relative virus control." (PMID 32760119, 2020). "However, an interesting finding is that, by 2 days post-infection, many of the genes associated with upregulation by interferons, such as Mx1, Mx2 and 2’5’ oligoadenylate synthase (OAS) demonstrate high levels of expression." (PMID 22713837, 2012). "Under a recessive model, MX1 rs7280422 was associated with symptomatic infection (OR = 0.19 [95% CI 0.08–0.42], p = 0.014) with the homozygous reference allele CC found significantly more often in asymptomatic WNV-positive controls than in WNV symptomatically infected individuals." (PMID 21935451, 2011). "As expected, transcripts encoding the proteins Mx1 and rHIV (a RNA helicase) showed 6.4- and 4.8-fold increases at 24 hours PI, respectively, and were induced between 0 and 12 h postPRRSV-infection." (PMID 22331987, 2010). "MX1 transcripts may have specific diagnostic utility in early pre-symptomatic infection." (PMID 39616162, 2024). "In parallel, infection with the VP3-D671A/Y677A mutant induced higher MX1 levels than parental virus, supporting a role for D671 and Y677 in modulating ISG responses." (PMID 40883306, 2025). "In contrast to SK6 cells, infection of PK-15 cells with PhoPeV resulted in the expression of ISGs such as Mx1." (PMID 39861896, 2025). "Consistent with our previous data, infection with the R191A-Nef HIV-1 CH042 induced substantially higher levels of MX1 expression than the WT virus." (PMID 41354661, 2025). "Infection induced a significant upregulation of pulmonary interferon-stimulated genes (ISGs), such as Mx1 and Isg20 (indicators of viral replication), as early as 2 dpi in both young and aged mice." (PMID 41145556, 2025). "We confirmed that Mx1 is expressed in bovine udders following infection of precision cut bovine udder slices with r-Tx/37-B3.13 and examining Mx1 and NP staining by immunohistochemistry and immunofluorescence." (PMID 41398153, 2025). "Volcano plots revealed that the most highly upregulated genes in response to OC43 infection, such as SOD2, CD44, STAT1 and MX1, were inflammation-associated genes and antiviral ISGs." (PMID 40368896, 2025). "Levels of Mx1 in the suboptimal-fat diet bats remained elevated throughout the experiment, while the other diets returned to pre-infection baselines." (PMID 39968620, 2025). "In H820 cells, IFNλ1 and MX1 mRNA levels were upregulated during infection with WSNΔNS1, and only a slight increase in IFNλ1 was observed in wild-type WSN-infected cells." (PMID 40434103, 2025). "Pre-infection Mx1 expression was similar between diets, although all bats were expressing detectable Mx1." (PMID 39968620, 2025). "All ISGs were downregulated in all infection groups at 14 dpi, with significant downregulation of MX1 and MX2 in the PJ73 group and JBNU-22-N01 group." (PMID 40459260, 2025). "In this regard, it was shown that the disruption of the Mx1 gene can lead to a severe loss of protective innate immunity against IAV in mice, resulting in severe infection and rapid death." (PMID 40565228, 2025). "The mRNA expression of IL-29, TNF-α and IFN-β for the G4 swine viruses were similar to the level achieved in G1, whereas the expressions of ISG15 and MX1 were particularly high in H1N1/pdm/09 infection." (PMID 40742730, 2025).
infection (continued). "The results indicate that LSDV ORF137 inhibits the transcription of IFN-β, ISG54, ISG56, and Mx-1 genes induced by cGAS-STING in HEK-293T cells post-HSV-GFP-infection." (PMID 41002440, 2025). "Consistent with the ectopic expression data, infection of RV with D671A and Y677A mutations in VP3 resulted in higher levels of MX1 expression in WT cells compared to infection of the parental viral strain." (PMID 40883306, 2025). "Compound 10 treatment elevated the expression of cellular antiviral genes, including Ifnb1, Isg15, Isg56, and Mx1, at 4 days post-infection (dpi)." (PMID 40298378, 2025). "Specifically, we observed an upregulation of antiviral genes, including rig-i, mx1, ifn-γ, irf3, and mda5, which are known to be crucial for effective antiviral responses in mucosal surfaces, particularly during the early stages of infection." (PMID 38218870, 2024). "The prominence of MX1 in the immune response to the EBOV highlights its potential role in the pathogenesis of the infection and underscores its significance as a key component of the host's defense mechanism against viral threats." (PMID 39282474, 2024). "Among time points in which at least one of these biomarkers was elevated ( > Z2) to signify replicative infection the ratio of MX1:IFI27 levels best correlated with time from virus challenge." (PMID 39616162, 2024). "Later during infection, at 12 dpi, the top ten significantly upregulated genes with highest fold change included, similar to 4 dpi, Zbp1, Oas2, Gbp1, Ddx60, Oas1a and Mx1." (PMID 38536871, 2024). "Blood MX1 expression is superior to IFI27 expression for diagnosis of early infection, as a correlate of viral load and for discrimination of virus culture positivity." (PMID 39616162, 2024). "We found that ASFV-WT infection strongly suppressed the mRNA levels of Isg56, Isg15, Mx1, and Oas2 induced by IFN-α." (PMID 38620034, 2024). "Expression of Mx1 was strongly up-regulated in both strains at day 3 p.i. after infection, with higher levels in D2-Mx1r/r mice and slightly decreased in both strains at day 5 p.i.." (PMID 38360537, 2024). "Mx1GFP × tgMx1CreRosa26lsl-tdT mice were infected with L.m.-gp66 and assessed for history of IFN signaling (i.e., Mx1 expression) in antigen-specific CD4+ T cells identified using LLO:I-Ab or gp66:I-Ab tetramers on day 7 after infection." (PMID 39321257, 2024). "We found that both the mRNA and protein levels of IFN-α, IFN-β, ISG56, and MX1 in PAMs induced by ASFV-intB318L infection were higher than those induced by ASFV-WT, especially at 24 hours post-infection (hpi)." (PMID 38620034, 2024). "It is well-known that mice carrying the functional Mx1 gene inhibits influenza A viral transcription and replication, rendering them resistant to infection." (PMID 39224597, 2024). "Compared to baseline (pre-infection) samples from the same individuals, increased levels of MX1 expression (Z > 2) were largely confined to early time points day 0-2 after presentation within 4 days of symptom onset." (PMID 39616162, 2024). "Similar results were observed at the transcript level on day two post-infection for antiviral genes Ifit3, Mx1, and Oas1, with SEOV inducing minimal gene expression." (PMID 39585900, 2024). "The knockdown of RIG-I inhibits the IFN pathway and the ectopic expression of ISG15 and MX1 inhibits the infection of FMDV." (PMID 38512977, 2024). "Using RT-qPCR for precise quantification, we observed an increase in the expression of PKR and Mx1 following H9N2 AIV infection indicative of the cellular response to viral invasion." (PMID 38731436, 2024). "Among individuals who developed replicative infection, blood MX1 transcript levels discriminated virus culture positivity in nose or throat samples with AUROC 0.85 (0.79-0.92), significantly better than IFI27 which achieved AUROC of 0.66 (0.57-0.75)." (PMID 39616162, 2024).
infection (continued). "The observed inhibition of PKR and Mx1 mRNA expression after H9N2 AIV infection underscores OMT’s potential to interfere with host–virus interactions at the molecular level, possibly through modulation of TLR3 signaling." (PMID 38731436, 2024). "The significant involvement of Interferon-Stimulated Genes (ISGs) like ISG15, OAS1, and MX1 throughout the infection period underscores the critical role of interferon responses." (PMID 38957806, 2024). "Similar to previous reports, the expression levels of IFIT1, IRF1, and MX1 in Znfx1–/– BMDMs were higher than those in WT BMDMs following H37Rv infection, despite the increased intracellular M. tuberculosis burden in Znfx1–/– BMDMs." (PMID 38016036, 2024). "Across all time points, IFI27 measurements achieved statistically better AUROC than MX1 measurements for discrimination of infection from baseline uninfected samples." (PMID 39616162, 2024). "In this study, we performed a detailed transcriptome analysis in the lungs of B6-Mx1r/r and D2-Mx1r/r mice carrying a functional Mx1 gene after infection with the influenza A virus." (PMID 38360537, 2024). "The response marker of the interferon (IFN)-α response, Mx1, revealed an early response with a main, statistically significant peak at day 2 post-infection." (PMID 39355243, 2024). "Myxovirus resistance protein 1 (MX1) has antiviral activity, and is closely related to the infection of the virus, which is very sensitive to the virus response or even a very small amount of the virus can induce cells to express MX1 protein." (PMID 37370417, 2023). "Two common antiviral genes, OAS1 and MX1, showed increased mRNA levels during the course of infection." (PMID 37724882, 2023). "The fact that several ISGs, such as Isg15, Igs56, and Mx1 are highly upregulated during infection suggests that infected cells release sufficient IFNβ to induce the expression of genes associated with antiviral defense mechanisms." (PMID 36851549, 2023). "MX1, OAS, IFIT1, and IFIT2 showed a significantly larger induction in the WT-infection compared to the ΔUL138STOP-infection either at 24 hpi for OAS or 48 hpi for MX1, IFIT1 and IFIT2." (PMID 37289831, 2023). "In the presence of VitD and rxrbb during GCRV infection, the double knockout of grass carp vdra and vdrb significantly induced the transcriptions of mda5, rig-I, mavs, tbk1, irf3, irf7, and mx1." (PMID 37466438, 2023). "Endogenous mRNA levels of the IFN-α, IFN-β and interferon-stimulated genes, IFIT1 and MX1, were measured at 0, 12, and 24 h post-infection." (PMID 36845118, 2023). "Compared to RTG2 cells, RTgill cells induced IFN early followed by MX1 induction and shut down during later stages of infection." (PMID 36851680, 2023). "Interferon-stimulated genes such as Isg15, Isg56 (IFIT1), and Interferon-induced GTP-binding protein Mx1 (Mx1) were strongly induced following infection." (PMID 36851549, 2023). "ACE2 and TMPRSS2 are involved in early stages of infection, while MX1 implication takes place in later stages." (PMID 37287057, 2023). "The infection of IFNβ promoter or MX1 promoter luciferase transfected cells demonstrated a 3-fold and 4-fold increase, respectively, in both IFNβ and MX1 promoter activity with VHSV Ia infection in G3BP1 KD cells compared to WT RTgill cells." (PMID 36851680, 2023). "As the natural infections of adult cattle with this virus remain almost asymptomatic, we suggest that the Mx1 protein participates in the innate control of the infection." (PMID 37243140, 2023). "In contrast, infection with RVA strains G9P{13] led to significant downregulation of the expression of MX1 (both viruses) and EIF2AK2 (PKR) (G9P only)." (PMID 37848925, 2023). "Pre-stimulation of THP-1 cells with LpOMV/SpMV increased IAV replication 24 h post infection (p.i.)compared to infected control (–-), whereas pre-treatment with Mx1-inducing OMVs (Kp/Ec/Sal) blocked IAV replication." (PMID 36978183, 2023).
infection (continued). "Similar to VHSV IVb, Ia strain shuts down IFN and MX1 induction in cells over-expressing MAVS or treated with exogenous IFN prior to infection." (PMID 36851680, 2023). "EPSTI1, NACAP1, SHROOM3, C19ORF35, and MX1 as the essential features play important roles in the infection and immune response to novel coronavirus." (PMID 35620480, 2022). "The present study showed that IFN-λ was more dominantly induced in the lung of SARS-CoV-2-infected hamsters from an early stage of infection and mediated the induction of ISGs such as Mx1, Rsad2, and IFIT3 preferentially from 3 dpi." (PMID 36524125, 2022). "IFI44, ISG15, MX1, RSAD2, SAMD9 and TNFSF10 were chosen as they are infection-associated genes that show lower expression levels in Holstein infected cells compared to Sahiwal cells." (PMID 35061738, 2022). "In NHBE cells, only MX1, MX2, and OAS1 were significantly over-expressed in SARS-CoV-2-infected cells compared with mock infection (p < 0.05 for MX1 and OAS1; and p < 0.01 for MX2)." (PMID 36298734, 2022). "Particularly, the IFN-induced GTP-binding antiviral protein MX1 was significantly elevated at both translation and proteome levels for all conditions for at least one time point post-infection." (PMID 35110370, 2022). "Flow cytometry analysis, using GFP expression as a marker for productive infection, demonstrated a near-complete block of infection in DoxOn A549-SunTag cells with active MX1 expression; DoxOff cells and cells expressing an NTG were not protected." (PMID 35421191, 2022). "In line with mRNA expression, percentage of MX1+ B cell increased and stayed high for seven days after in vitro infection." (PMID 34169553, 2022). "The expressions of il10, nos2 and the ISGs isg15, and mx1 were only upregulated in tlr2−/− macrophages following infection, indicating that TLR4 controls the levels of these M(Kp) markers." (PMID 36337046, 2022). "In head kidney, Mx2 also showed the strongest and quickest response, with maximum expression at 24 h post-infection, followed by Mx1, which showed a weak response detected at 24 h post-infection." (PMID 36009736, 2022). "Further, SARS-CoV-2 infection significantly induced these ISGs in ferret tracheal biopsy samples collected on day 3 after infection compared with mock-treated animals (p < 0.01 for MX1; and p < 0.05 for MX2, ISG15, and OAS1)." (PMID 36298734, 2022). "Among challenged animals, Nsp1-K164A/H165A vaccination specifically reduced viral loads in the respiratory tract and suppressed infection-induced macrophage accumulation and MX1 upregulation in the lung." (PMID 36380761, 2022). "IF data indicated that MX1 protein levels were most elevated between 96h and 120h post-infection and this coincided with diminishing ZIKV-positive SC." (PMID 34079533, 2021). "For the interferon regulated genes, Ct infection induced a significant increase in the MX1 and MX2 mRNA fold change (between ~2 and 3.5) at 12, 24 and 36 hpi, while CMPk2 mRNA fold change increased between 36 and 48 hpi to ~2.6 and 2, respectively." (PMID 34684219, 2021). "The stimulatory effect of IFNT on RSAD2, IFIT3 and MX1 was inhibited to a greater extent by HO infection and only HO inhibited GBP4 and HERC5 expression." (PMID 33898551, 2021). "In particular, an increased expression of ANXA6 is observed soon after HL-mEC infection, which declines over time concomitantly to the enhanced expression of MX1." (PMID 34361874, 2021). "Treatment with ΔNS1 resulted in the early induction (24 h post infection) of Mx1 specific mRNA in both A2G and BALB/c mice." (PMID 34773048, 2021). "By days 5 and 7 of infection, there was a marked difference in gene expression with heightened expression of Mx1, Tlr3, Ifnα2, Ifnαr1, Ifnβ1, and Il-15 detected in aged lung in response to H1N1." (PMID 34829979, 2021). "Treatment with ΔNS1 resulted in the early induction (24 hours post infection) of Mx1 specific mRNA in both A2G and BALB/c mice." (PMID 34401874, 2021).
infection (continued). "As expected, IAV infection also resulted in increased expression of Ifit2, Mx1, and Oasl2 over mock infection." (PMID 33593970, 2021). "Consistent with our LC-MS/MS data, IF staining showed that MX1 protein was nearly undetectable at 24 h, but then increased significantly by 48 h post-infection." (PMID 34079533, 2021). "Taken together, these data demonstrate that the expression of antiviral type I IFN responses (IFNβ and Mx1) and pro-inflammatory cytokine responses (IL-8) in the BF was reduced following infection with the vv strain compared to the classical strain." (PMID 32582573, 2020). "For example, we found a lncRNA potentially transcribed in an intron of MX1 (MLUGL00000039178) up-regulated (log2 fc = 3.36) during infection." (PMID 32289119, 2020). "The increase in MX1 at the peak of infection mirrors the increases observed in situ in AGMs and RMs." (PMID 32119719, 2020). "Subsequently, the mRNA levels of RIG-1, PKR, and Mx1 gene began to increase at 12 h post-infection, whereas the expression of OAS1 continued to significantly decline (P < 0.01)." (PMID 32133381, 2020). "Real-time quantitative polymerase chain reaction was used to detect differences in the expression of the RIG-1, PKR, OAS1, Mx1, and Mx2 genes at various time points post-infection." (PMID 32133381, 2020). "Both viruses replicated to high titers in liver, lung and spleen of Mx1-/- mice at four days after intraperitoneal (i.p.)infection, but were potently restricted in Mx1+/+ animals." (PMID 33196685, 2020). "In order to evaluate a potential direct effect of MX1 on infection, THP-1 cells or BDMs were transfected with an siRNA-pool targeting MX1 (siMX1)." (PMID 32209695, 2020). "At 48 h post-infection, viral protein remained increased, and additional differentially expressed proteins were present, including MX1 and CXCL6." (PMID 32093375, 2020). "The expression of RIG-1, PKR, OAS1, Mx1, and Mx2 were significantly and positively correlated to each other during the entire infection (P < 0.01)." (PMID 32133381, 2020). "MX1 protein confers antiviral function in transfected cells and transgenic animals and can protect against lethal infection by influenza virus in a mouse model." (PMID 32183248, 2020). "Results show that, compared to r19F-infected animals, r19FCX4C-infected animals produced significantly lower levels of cytokines/chemokines (IFN-γ, MCP-1, and TNF-α or an antiviral protein (MX1) at day five post infection." (PMID 31330970, 2019). "Concordantly, the expression of myxovirus resistance 1 (MX1) has been reported to be up-regulated in PRRSV infected pulmonary alveolar macrophages over 24 h post infection period." (PMID 31536525, 2019). "The next gene marker tested was a 275-bp insertion in the proximal promoter of the MX1 gene (MX Dynamin Like GTPase 1), which enhances the transcriptional activity of this gene, mediating the humoral response to infection with PRRSV." (PMID 31374992, 2019). "TSVE moderately up-regulated the mRNA level of IL-6, IL-8, TNF-α, IFN-β, CXCL9 and MX1 over the infection time." (PMID 30866776, 2019). "Although untreated control mice began to succumb to infection at day 9, Mx1-9R-treated mice displayed rapid recovery from body weight loss and demonstrated decreased mortality compared with the untreated control." (PMID 30696001, 2019). "In humans, the type I and III interferon (IFN)-induced large dynamin-like GTPase Mx1 (in humans commonly known as MxA) represents a potent interspecies barrier that restricts such spill-over infections." (PMID 30945621, 2019). "Pre-infection Mx1-9R treatment efficiently reduced the viral titer in PR8-infected MDCK-cell culture supernatant while recombinant 9 arginine conjugated ovalbumin (OVA-9R) proteins did not inhibit the viral replication of PR8." (PMID 30696001, 2019). "Except gene mx-1, most of the genes showed log2 fold change ≥2 or even ≥10 at 24 or 72 h post-infection, whereas the expression level decreased at 8 h post-infection." (PMID 29415502, 2018).